ZC3H6 (zinc finger CCCH-type containing 6)
Synonyms: KIAA2035; ZC3HDC6; FLJ41410; FLJ45877
Tractability: No criterion of Open Targets' tractability assessment is met for any kind of drug.
Gene: Protein-coding gene on chromosome 2 (112,275,597 to 112,340,059, forward strand). Ensembl gene ENSG00000188177.
Subcellular location (Human Protein Atlas): Golgi apparatus; Nucleoplasm
Gene Ontology:
Molecular function: DNA-binding transcription repressor activity, RNA polymerase II-specific; metal ion binding; RNA binding
Biological process: negative regulation of DNA-templated transcription, elongation; negative regulation of DNA-templated transcription; negative regulation of transcription by RNA polymerase II
Cellular component: chromatin; nucleoplasm; nucleus
Genetic constraint (gnomAD): Loss-of-function variants: 32 observed, 84.14 expected, observed/expected ratio (o/e) 0.38, 90% interval 0.29 to 0.51. The upper end of that interval is the gene's LOEUF score, 0.51, which puts it in group 2 of 6, group 1 being the genes least tolerant of losing a copy. Missense variants: 1,153 observed, 1,279.6 expected, observed/expected ratio (o/e) 0.9, 90% interval 0.86 to 0.95. Synonymous variants: 441 observed, 454.91 expected, observed/expected ratio (o/e) 0.97, 90% interval 0.9 to 1.05.
Homologues: Orthologues: chimpanzee ZC3H6 (99% identical), macaque ZC3H6 (98% identical), pig ZC3H6 (88% identical), dog ZC3H6 (87% identical), rabbit ZC3H6 (87% identical), guinea pig ZC3H6 (81% identical), mouse Zc3h6 (77% identical), rat Zc3h6 (73% identical), tropical clawed frog zc3h6 (42% identical), zebrafish zc3h6 (39% identical). Paralogues in human: ZC3H4 (36% identical), ZC3H8 (13% identical).